ENSG00000268533 (novel protein)
Gene: Protein-coding gene on chromosome 19 (57,394,183 to 57,438,457, forward strand). Ensembl gene ENSG00000268533.
Genetic constraint (gnomAD): Loss-of-function variants: 2 observed, 1.93 expected, observed/expected ratio (o/e) 1.04, 90% interval 0.37 to 1.88. That is too few expected variants to judge how well the gene tolerates losing a copy. Missense variants: 19 observed, 13.6 expected, observed/expected ratio (o/e) 1.4, 90% interval 0.97 to 1.88. Synonymous variants: 4 observed, 4.41 expected, observed/expected ratio (o/e) 0.91, 90% interval 0.44 to 1.78.